ENSG00000285749 (novel protein)
Gene: Protein-coding gene on chromosome 3 (51,798,803 to 51,830,856, forward strand). Ensembl gene ENSG00000285749.
Genetic constraint (gnomAD): Loss-of-function variants: 7 observed, 5.89 expected, observed/expected ratio (o/e) 1.19, 90% interval 0.66 to 1.86. That is too few expected variants to judge how well the gene tolerates losing a copy. Missense variants: 189 observed, 201.48 expected, observed/expected ratio (o/e) 0.94, 90% interval 0.83 to 1.06. Synonymous variants: 82 observed, 76.02 expected, observed/expected ratio (o/e) 1.08, 90% interval 0.9 to 1.3.